UBE2B (ubiquitin conjugating enzyme E2 B)
Description:
E2 ubiquitin-conjugating enzyme that accepts ubiquitin from the ubiquitin-activating enzyme E1 and transfers it to a E3 ubiquitin-protein ligase. In vitro catalyzes 'Lys-11'-, as well as 'Lys-48'- and 'Lys-63'-linked polyubiquitination. Together with the E3 enzyme BRE1 (RNF20 and/or RNF40), plays a role in transcription regulation by catalyzing the monoubiquitination of histone H2B at 'Lys-120' to form H2BK120ub1. H2BK120ub1 gives a specific tag for epigenetic transcriptional activation, elongation by RNA polymerase II, telomeric silencing, and is also a prerequisite for H3K4me and H3K79me formation. May play a role in DNA repair. Associates to the E3 ligase RAD18 to form the UBE2B-RAD18 ubiquitin ligase complex involved in mono-ubiquitination of DNA-associated PCNA on 'Lys-164'. In association with the E3 enzyme UBR4, is involved in N-end rule-dependent protein degradation. May be involved in neurite outgrowth (By similarity).
Synonyms: HR6B; hHR6B; RAD6B; UBC2; E2-17kDa
Tractability: Antibody: UniProt places it where antibodies can reach, with medium confidence; its Gene Ontology location is reachable by antibodies, with medium confidence; the Human Protein Atlas places it where antibodies can reach. PROTAC: ubiquitination databases record sites on it; a small molecule that binds it is known.
Target class: Enzyme; Aminoacyltransferase
Gene: Protein-coding gene on chromosome 5 (134,371,184 to 134,393,959, forward strand). Ensembl gene ENSG00000119048.
Subcellular location: Cell membrane; Nucleus
Subcellular location (Human Protein Atlas): Cytosol; Nucleoplasm; Plasma membrane; Flagellar centriole; Mid piece; Principal piece; Vesicles
Pathways (Reactome):
Metabolism of proteins: E3 ubiquitin ligases ubiquitinate target proteins; Synthesis of active ubiquitin: roles of E1 and E2 enzymes
DNA Repair: Recognition of DNA damage by PCNA-containing replication complex
Immune System: Antigen processing: Ubiquitination & Proteasome degradation
Gene Ontology:
Molecular function: protein binding; ubiquitin conjugating enzyme activity; ubiquitin protein ligase binding; ubiquitin-protein transferase activity; ubiquitin-like protein transferase activity
Biological process: DNA damage response; DNA damage tolerance; DNA repair; proteasome-mediated ubiquitin-dependent protein catabolic process; protein autoubiquitination; protein K11-linked ubiquitination; protein K48-linked ubiquitination; protein K63-linked ubiquitination; protein stabilization; protein ubiquitination; response to UV; response to xenobiotic stimulus; ubiquitin-dependent protein catabolic process; positive regulation of canonical Wnt signaling pathway; protein polyubiquitination; spermatogenesis
Cellular component: cytoplasm; HULC complex; nucleus; replication fork; chromatin; nucleoplasm; plasma membrane; XY body
Genetic constraint (gnomAD): Loss-of-function variants: 8 observed, 15.49 expected, observed/expected ratio (o/e) 0.52, 90% interval 0.3 to 0.93. The upper end of that interval is the gene's LOEUF score, 0.93, which puts it in group 3 of 6, group 1 being the genes least tolerant of losing a copy. Missense variants: 58 observed, 130.55 expected, observed/expected ratio (o/e) 0.44, 90% interval 0.36 to 0.55. Synonymous variants: 60 observed, 48.23 expected, observed/expected ratio (o/e) 1.24, 90% interval 1.01 to 1.54.
Homologues: Orthologues: guinea pig UBE2B (100% identical), macaque UBE2B (100% identical), mouse Ube2b (100% identical), pig UBE2B (100% identical), rat Ube2b (100% identical), tropical clawed frog ube2b (97% identical), chimpanzee UBE2B (95% identical), rabbit UBE2B (93% identical), zebrafish ube2b (93% identical), Drosophila melanogaster Ubc6 (84% identical). Paralogues in human: UBE2A (95% identical), UBE2C (43% identical), UBE2N (41% identical), UBE2R2 (40% identical), UBE2I (39% identical), CDC34 (38% identical), UBE2NL (37% identical), UBE2W (36% identical), UBE2T (34% identical), UBE2G2 (33% identical), UBE2Z (33% identical), UBE2U (32% identical), and 12 more.
Diseases named in the same sentence as UBE2B in open-access papers:
UBE2B is named in the same sentence as 53 diseases in open-access papers, as found by Europe PMC text mining. Sharing a sentence is not in itself a finding about the gene and the disease. The quoted sentences say what the papers report.
breast carcinoma (7 papers, 2011 to 2022). "UBE2B (also known as hHR6B or Rad6B) is an E2 enzyme which may play a role in breast cancer development." (PMID 36139159, 2022).
Azoospermia (3 papers, 2015 to 2025). Absence of any measurable level of sperm,whereby spermatozoa cannot be observed even after centrifugation of the semen pellet. "Moreover, an Ube2b gene promoter variant is detected in idiopathic azoospermia patients, and the Ube2b variant confers a high risk for azoospermia patients in a Chinese population." (PMID 34632937, 2021). "In this study, we sequenced the exon and promoter region of UBE2B in 776 patients diagnosed with idiopathic azoospermia (IA) and 709 proven fertile men to examine whether UBE2B is involved in the pathogenesis of IA." (PMID 26223869, 2015). "A patient biopsy (No. 188) with UBE2B Chr5.133706925 A > G confirmed the diagnosis of non-obstructive azoospermia." (PMID 26223869, 2015). "In this study, a biopsy of a patient (No. 188) with the UBE2B Chr5.133706925 A > G confirmed the diagnosis of non-obstructive azoospermia and further histopathology showed abnormal spermatogenesis." (PMID 26223869, 2015).
male infertility (3 papers, 2015 to 2025). The inability of the male to effect fertilization of an ovum after a specified period of unprotected intercourse. "Previous studies have shown that the variants of UBE2B are associated with male infertility in humans." (PMID 26223869, 2015). "Ube2b-deficient mice showed male infertility and sperm head shape anomalies." (PMID 27835637, 2016). "Therefore, the objective of this study was to determine the association between UBE2B gene variants and male infertility." (PMID 26223869, 2015).
ovarian carcinoma (3 papers, 2022 to 2024). A malignant neoplasm originating from the surface ovarian epithelium. "Therefore, attention has been drawn towards UBE2B, which has been observed to facilitate the progression of cancer in diverse types, including rectal, nasopharyngeal, and ovarian carcinoma." (PMID 38481990, 2024). "Consequently, the activation of UBE2B leads to the enhancement of stem cell gene expression and promotion of malignant characteristics in ovarian cells, thereby contributing to chemotherapy resistance, metastasis, and recurrence in patients with ovarian cancer." (PMID 38481990, 2024).
infertile (2 papers, 2022 to 2025). "A previous study in mice showed that UBE2B knock-outs were infertile due to abnormal spermatogenesis." (PMID 41392145, 2025).
melanoma (2 papers, 2019 to 2021). A malignant, usually aggressive tumor composed of atypical, neoplastic melanocytes. "As Rad6 is encoded by two genes, namely, UBE2A (RAD6A) and UBE2B (RAD6B), in humans, we compared their expressions in melanomas and normal melanocytes." (PMID 31683936, 2019).
oral cancer (2 papers, 2018 to 2021). "It was found that miR-455-5p expression is regulated by the TGF-β-dependent pathway, which subsequently leads to UBE2B [Ubiquitin-conjugating enzyme E2B] down-regulation and contributes to oral cancer tumourigenesis." (PMID 33507694, 2021). "It has been reported that miR-455-3p up-regulation is controlled by the TGF-beta pathway, consequently down-regulating ubiquitin conjugating enzyme E2B gene (UBE2B), which results in oral cancer proliferation." (PMID 29482431, 2018).
rectal cancer (2 papers, 2021 to 2022). A primary or metastatic malignant neoplasm that affects the rectum. "For instance, high expression of UBE2B is closely associated with poor response and low survival rate in rectal cancer patients following chemoradiotherapy." (PMID 34632937, 2021).
retinal degeneration (2 papers, 2024 to 2025). Degeneration of the retina. "To this purpose, we expressed human UBE2B (homologous to Ubc6, DIOPT homology score = 13) and human UBE2D2 and UBE2D4 (homologous to eff, DIOPT scores of 13 and 10, respectively) and compared their capacity to rescue retinal degeneration compared to mock mcherry overexpression." (PMID 39879147, 2025). "On this basis, we expressed human UBE2B (homologous to Ubc6, DIOPT homology score=13) and human UBE2D2 and UBE2D4 (homologous to eff, DIOPT scores of 13 and 10, respectively) and compared their capacity to rescue retinal degeneration compared to mock mcherry overexpression." (PMID 38168249, 2024).
squamous cell carcinoma (2 papers, 2022 to 2024). A carcinoma arising from squamous epithelial cells. "Specifically, high expression of UBE2B was associated with poorer survival outcomes, especially in cases of squamous cell carcinoma." (PMID 38481990, 2024).
triple-negative breast carcinoma (2 papers, 2011 to 2024). An invasive breast carcinoma which is negative for expression of estrogen receptor (ER), progesterone receptor (PR), and human epidermal growth factor receptor 2 (HER2). "In addition to its involvement in the progression of oral squamous cancer, UBE2B also played a role in enhancing the cisplatin resistance of triple-negative breast cancer." (PMID 38481990, 2024).
myeloid leukemia (1 paper, 2008). A clonal proliferation of myeloid cells and their precursors in the bone marrow, peripheral blood, and spleen. "Expression of the genes beclin-1 and ube2b was found to be decreased in myeloid leukemia cell lines and primary AML cells in which CREB was downregulated." (PMID 18801183, 2008).
nasopharyngeal carcinoma (1 paper, 2021). A carcinoma arising from the nasopharyngeal epithelium. "UBE2B regulates the sensitivity of nasopharyngeal carcinoma (NPC) cells to carmustine (BCNU) by ubiquitination of MGMT (a DNA repair enzyme)." (PMID 33810518, 2021).
oral squamous cell carcinoma (1 paper, 2019). "In oral squamous cell carcinoma, miR‐455‐5p expression was promoted by the regulation of the TGF‐β‐dependent pathway and contributed to cancer tumorigenesis by downregulating UBE2B expression." (PMID 30444038, 2019).
X-linked intellectual disability (1 paper, 2024). An X-linked intellectual deficiency in which not enough information is known, reported or published to indicate whether a gene causes non-syndromic or syndromic presentations. "Ube2b, a member of family 2, is required for neurite growth and is the paralog of Ube2a, the murine orthologue of UBE2A mutated in X-linked intellectual disability." (PMID 39596581, 2024).
cancer (10 papers, 2011 to 2024). A tumor composed of atypical neoplastic, often pleomorphic cells that invade other tissues. "Further investigations of UBE2B expression in unpaired samples of pan-cancer revealed diverse expression levels observed across different types of cancers." (PMID 38481990, 2024). "Studies reported that UBE2B acted as a positive regulator of the canonical Wnt signaling pathway by affecting the stability and activity of β-catenin, promoting cancer development." (PMID 38481990, 2024). "As such, targeting UBE2B may present a promising therapeutic approach for the prevention and treatment of various cancers." (PMID 38481990, 2024). "UBE2B exhibited significant upregulation and was found to be correlated with survival outcomes in ESCA as well as other cancer types." (PMID 38481990, 2024).
tumor (5 papers, 2011 to 2024). "In this study, it was intriguingly observed that these signaling pathways and biological processes that promote the aggressive behavior of tumor cells were enriched specifically in patients with ESCA who had high expression of UBE2B." (PMID 38481990, 2024). "However, the specific E3 ligases that interact with UBE2B in ESCA and contribute to its role in tumor development are not yet fully understood." (PMID 38481990, 2024).
UBE2B also shares sentences with these, for which no sentence is quoted: infection (20 papers); viral infection (5); cervical carcinoma (3); Esophageal carcinoma (2); metastatic melanoma (2); adenocarcinoma (1); asthenozoospermia (1); atrial fibrillation (1); benign papillomas (1); breast tumors (1); Cachexia (1); cervical intraepithelial neoplasia (1); cervical neoplasms (1); colon cancer (1); congenital heart disease (1); cutaneous melanoma (1); demyelinating disease (1); esophageal adenocarcinoma (1); gastric cancer (1); leukemia (1); lung carcinoma (1); lymphoma (1); malignant peripheral nerve sheath tumor (1); meningioma (1); myeloma (1); neurological diseases (1); non-small cell lung carcinoma (1); nosocomial infection (1); Obesity (1); oligospermia (1).
A further 6 diseases each share a sentence with UBE2B in 1 paper.